CTSB (cathepsin B)
Diseases named in the same sentence as CTSB in open-access papers (continued):
Sharing a sentence is not in itself a finding about the gene and the disease.
psoriasis (7 papers, 2019 to 2025). An autoimmune condition characterized by red, well-delineated plaques with silvery scales that are usually on the extensor surfaces and scalp. "Meanwhile, this was the case for 16 of the itch-associated genes in MCs isolated from psoriasis skin, including CTSB, TLR4, and TACR1 (training set AUC OOB = 1, OOB Error rate = 11.11%, validation set AUC = 0.875, 95% CI = 0.63–1)." (PMID 37681909, 2023). "Total cathepsin B+ cells (mean frequency of 151.4 ± 16.61/mm2 vs. 373.3 ± 30.93/mm2 (mean ± SEM) **** p < 0.0001) were found to be significantly increased in psoriasis skin." (PMID 37681909, 2023). "Because human tryptase is a PAR-2 ligand, the significant upregulation of CTSB in MCs in psoriasis lesions and the correlation of cathepsin B with PASI would suggest a contribution to promoting PAR-2 signalling in sensory nerve fibres." (PMID 37681909, 2023). "In both whole-skin published datasets and isolated MCs, CTSB was found to be a reliable indicator of the psoriasis condition." (PMID 37681909, 2023). "Cathepsin B was widely expressed in the epidermis and dermis of normal and psoriasis skin, including in MCs." (PMID 37681909, 2023). "In our random forest analyses, CTSB was the only gene common to the psoriasis whole-skin datasets and isolated MCs which was a significant indicator of the psoriasis condition." (PMID 37681909, 2023). "Targeting CTSB, the gene responsible for cathepsin B, may present the opportunity for a novel anti-inflammatory therapy for psoriasis." (PMID 39337637, 2024). "While the downregulation of cathepsin B in keratinocytes has been shown to reduce their proliferation and inflammatory response, the silencing of CTSB expression in MCs could become a means of controlling MC-induced itch in psoriasis." (PMID 37681909, 2023). "Therefore, we investigated changes in cathepsin B expression in psoriasis skin via immunofluorescence microscopy." (PMID 37681909, 2023). "Although cathepsin B+ MC density was not significantly increased (37.85 (14.42–63.96) vs. 35.21 (13.20–103.8) (Median (IQR)), the density of cathepsin B+ MCs did significantly correlate with psoriasis severity (r = 0.74, * p = 0.0225), whereas the total cathepsin B+ cell number did not." (PMID 37681909, 2023). "Furthermore, we observed an increase in cathepsin B expression in psoriasis skin, an increase in the density of cathepsin B+ MCs correlating to PASI, and cathepsin B protease release from MCs in response to SP activation." (PMID 37681909, 2023). "CTSB was the only gene to be significantly upregulated in MCs as well, suggesting that Cathepsin B could serve as common indicator of MC-dependent itch signature in psoriasis." (PMID 37681909, 2023). "Furthermore, cathepsin B+ cells were increased in psoriasis skin and cathepsin B+ MC density correlated with disease severity." (PMID 37681909, 2023). "Furthermore, we found that CTSB expression can serve as an indicator of MC involvement in the itch signature of psoriasis, and that MC cathepsin B expression correlates with psoriasis severity." (PMID 37681909, 2023). "Therefore, our study provides evidence that cathepsin B could serve as a common indicator of the MC-dependent itch signature in psoriasis." (PMID 37681909, 2023). "Transcriptomic analysis has revealed an accumulation of cathepsin B-positive MCs (CTSB+ MCs) in psoriatic lesions, whose density correlates positively with Psoriasis Area and Severity Index (PASI) scores." (PMID 41164192, 2025). "CTSB, JAK1, and LTB4R were the only genes found by random forest analysis to be significant indicators of the psoriasis condition in both the whole skin datasets and isolated MCs." (PMID 37681909, 2023). "Furthermore, the inflammatory indicators found to be upregulated in psoriasis MCs, such as ATF4, CXCL12, LTA, TACR1, TLR4, and CTSB, interestingly share IL-1β as a common modulator." (PMID 37681909, 2023).
squamous cell carcinoma (7 papers, 1997 to 2024). A carcinoma arising from squamous epithelial cells. "Conversely, reverse Mendelian randomization analyses suggest that squamous carcinoma may lead to increased cathepsin B levels." (PMID 37805623, 2023). "Squamous cell carcinomas might regulate cathepsin B expression through transcription factors Ets1, Sp1, and Sp335, ultimately leading to immune resistance and tumor progression." (PMID 37805623, 2023). "Additionally, squamous cell carcinoma may play an important role in regulating cathepsin B expression." (PMID 37805623, 2023).
acute myeloid leukemia (6 papers, 2020 to 2025). Acute myeloid leukemia (AML) is a group of neoplasms arising from precursor cells committed to the myeloid cell-line differentiation. "Studies have shown that overexpression of CTSB in acute myeloid leukemia (AML) cells is related to a poor prognosis, and inhibition of CTSB in these cells contributes to the mechanism of apoptosis." (PMID 37446393, 2023).
adenoma (6 papers, 2008 to 2024). A neoplasm arising from the epithelium. "This aligns with previous work showing that mRNA levels of CTSB and CTSD increase concurrently with APC gene mutations that initiate the adenoma-adenocarcinoma sequence." (PMID 34428252, 2021). "They evaluated the probe in the widely used APCmin/+ mouse model of CRC and could show a specific activation of their cathepsin B probe in mouse adenomas using whole body fluorescence imaging." (PMID 35280747, 2022). "Subsequent studies used cathepsin B probes for endoscopic molecular imaging of adenomas in mice." (PMID 35280747, 2022). "Finally, by performing an in silico analysis, we describe the mRNA expression of ACE2, TMPRSS2 and the genes encoding their co-receptors CTSB, CTSL and FURIN in normal adrenal and adrenocortical tumors (both adenomas and carcinomas)." (PMID 34594302, 2021).
co-infection (6 papers, 2017 to 2025). "Cathepsin B and F in B. tabaci are highly expressed during viral co-infection or host switching, regulating virus acquisition and transmission." (PMID 41302824, 2025). "Several experiments were conducted to investigate the effects of cathepsin B on the transmission of ToCV in B. tabaci MED infected by co-infection and single infection." (PMID 37007483, 2023). "We verified the hypothesis that a decrease in cathepsin B after co-infection could promote ToCV transmission by B. tabaci." (PMID 37007483, 2023). "In this study, we verified the hypothesis that the relative expression and enzyme activity of cathepsin B were increased after co-infection, which helped to promote ToCV transmission by B. tabaci MED." (PMID 37007483, 2023). "Altogether, these results indicate that silencing of CstC impacts cathepsin B, L, and S activities in the endocytic pathway during Mtb and HIV mono-infections and during coinfection." (PMID 34867965, 2021). "Here in the context of infected Mø with Mtb or during co-infection with HIV, we first aimed to assess the effect of HIV PIs saquinavir (SQV) and ritonavir (RTV) on omnicathepsin proteolytic activities (which measure the combined activities of cathepsin B, L, and S)." (PMID 33841429, 2021).
cyst (6 papers, 2009 to 2019). A sac-like closed membranous structure that may be empty or contain fluid or amorphous material. "Seven genes that were differentially expressed were downregulated in the cyst, including the 16S rRNA gene, small subunit ribosomal RNA gene, 18S rRNA gene, cytochrome C oxigdase subunit I gene, cytochrome b gene, cathepsin B gene and the α-tubulin gene." (PMID 26079518, 2015). "The expression level of the cathepsin B gene in the cyst was clearly downregulated compared with the vegetative cell, which suggested that lysosome system played a minor role in degradation of proteins during the encystation because cathepsin B is a hydrolase of the lysosome system." (PMID 26079518, 2015).
fibrosis (6 papers, 2016 to 2025). the formation of excess fibrous connective tissue in an organ or tissue in a reparative or reactive process. "Liver stem cell-derived exosomes rich in miR-142a-5p, prevented the switch of macrophages toward M1 polarization and facilitated M2 polarization through targeting cathepsin B to suppress fibrosis in the CCl4-induced fibrosis mouse model." (PMID 39599900, 2024). "Taken together, our findings identify a pathomechanism whereby free or AM-bound IL-18 triggers proteolysis at PAJs through Cathepsin B, irrigating lungs with pre-made ECM which further activates myofibroblasts to trigger and perpetuate chronic fibrosis." (PMID 39747171, 2025). "ROS production and cathepsin B release, with both ROS and cathepsin B being agonists of NLRP3, promote the occurrence of pulmonary inflammation and the formation of fibrosis." (PMID 34944017, 2021).
human African trypanosomiasis (6 papers, 2015 to 2026). A parasitic disorder caused by protozoa of the Trypanosoma brucei species. "Trypanosoma brucei cysteine protease Cathepsin B (TbCatB) is a protein that is a potential drug target to treat sleeping sickness." (PMID 25931062, 2015).
inflammatory breast carcinoma (6 papers, 2011 to 2023). An advanced, invasive breast adenocarcinoma characterized by the presence of distinct changes in the overlying skin. "It has been reported that blocking uPAR and CTSB expression results in a significant reduction in inflammatory breast cancer cell migration and invasion." (PMID 37576397, 2023). "In line with this assumption, cathepsin B has been suggested to a potential prognostic marker for inflammatory breast cancer." (PMID 23773529, 2013). "Furthermore, CTSB and CTSH have been reported to be overexpressed in inflammatory breast cancer, as well as involved in cancer progression and invasion." (PMID 24932247, 2014).
Insulin resistance (6 papers, 2020 to 2025). Increased resistance towards insulin, that is, diminished effectiveness of insulin in reducing blood glucose levels. "In summary, CTSL1 expression in human SCAT is positively associated with adiposity, while SCAT CTSB expression is inversely related to whole-body insulin resistance." (PMID 32486882, 2020). "CTSB codes for a lysosomal protease of which the expression and activity are impaired in adipose tissue of obese rodents and its expression is also associated with insulin resistance." (PMID 38581663, 2024). "Here we assess the relation between abdominal subcutaneous AT (SCAT) CTSL1 and CTSB gene expression (qRT-PCR), body composition and tissue-specific insulin resistance in 77 overweight/obese (BMI: 225.6–38.6 kg/m2) well phenotyped men and women (61 M/16 F)." (PMID 32486882, 2020). "Our data show that reduced CTSB expression is associated with markers of insulin resistance (standardized β = −0.561, p < 0.001), independent of adiposity, while CTSL1 expression is only associated with markers of body composition." (PMID 32486882, 2020). "Interestingly, a reduced SCAT CTSB mRNA expression was associated with increased whole-body insulin resistance (i.e. fasting glucose, insulin and HOMA-IR), independent of adiposity, while an increased SCAT CTSL1 mRNA expression was only associated with adiposity (i.e. BMI and WHR)." (PMID 32486882, 2020).
meningioma (6 papers, 2012 to 2023). A generally slow growing tumor attached to the dura mater. "TGF-β1 induces the invasion of malignant meningioma cells with associated upregulation of uPA, CTSB, and MMP-9, and uPAR and CTSB act upstream in TGF-β1-initiated signaling." (PMID 37576397, 2023). "Cathepsin B has been considered a marker for malignancy in the more aggressive type of meningiomas; developing inhibitors of these peptidases might help control local spread." (PMID 22995409, 2012).
metastatic tumors (6 papers, 2005 to 2021). "Conversely we observed genes associated with aggressive metastatic disease and EMT (VIM, SPARC, ZEB1, SNAI2, CTSB) upregulated in lung populations compared to lymph nodes." (PMID 34579762, 2021). "CTSB-shRNA reduced lung metastatic nodules and prolonged survival in mice bearing experimental lung metastatic tumors." (PMID 24139065, 2013). "We next investigated whether CTSB-shRNA could inhibit lung metastatic tumors." (PMID 24139065, 2013). "We next investigated whether CTSB-shRNA could inhibit metastatic tumors in the lungs." (PMID 24139065, 2013). "Elevated cathepsin B (CTSB) and cathepsin D (CTSD) levels were detected in primary and metastatic tumor tissues of various cancer types." (PMID 26995190, 2016).
myocarditis (6 papers, 2018 to 2025). Myocarditis is a condition that is characterized by inflammation of the heart muscle (myocardium). "Conversely, the knockout of cystatin C escalated CTSB expression, boosted inflammasome activation, intensified myocardial cell pyroptosis and exacerbated myocarditis." (PMID 39248527, 2024). "CTSB can aggravate coxsackievirus B3-induced myocarditis by activating inflammasomes to promote pyroptosis." (PMID 37576397, 2023). "Recently, it has been found that CTSB is also involved in the pathological processes of many inflammatory diseases—for example, CTSB was significantly upregulated in coxsackievirus B3-induced myocarditis tissues, and CTSB knockout mice exhibited less inflammatory cell infiltration." (PMID 38711511, 2024). "Therefore, CTSB can enhance cell pyroptosis by triggering inflammasomes and exacerbate CVB3‐induced myocarditis, suggesting that CTSB inhibitors could offer a promising avenue for the treatment of CVB3‐induced myocarditis." (PMID 39248527, 2024). "The suppression of CTSB significantly mitigated inflammasome activation, reduced caspase‐1‐induced cell pyroptosis, minimized inflammation and cell damage in the heart and enhanced cardiac function affected by myocarditis, ultimately increasing the survival rate in mice." (PMID 39248527, 2024).
non-small cell lung carcinoma (6 papers, 1999 to 2024). A group of at least three distinct histological types of lung cancer, including non-small cell squamous cell carcinoma, adenocarcinoma, and large cell carcinoma. "For example, paclitaxel poliglumex, which triggers disruption of the lysosomal integrity followed by cathepsin B release and cell death, has shown efficacy for patients with advanced non-small cell lung carcinoma in a phase III clinical trial." (PMID 22574158, 2012). "In order to evaluate the possible role of the proteolytic enzyme cathepsin B (cath B) in human non-small cell lung cancer (NSCLC) we examined cath B concentrations (cath Bc) and activities (cath BA) in homogenates of 127 pairs of lung tumour tissues and corresponding non-tumourous lung parenchyma." (PMID 10507778, 1999). "A similar mechanism was shown in non-small cell lung cancer (NSCLC) cells, where the microtubules stabilizing agent paclitaxel activates the release of CtsB via disruption of lysosomes in the cell cytoplasm, favoring cell death." (PMID 31340550, 2019).
synucleinopathy (6 papers, 2019 to 2025). A neurodegenerative disease that is characterized by the abnormal accumulation of aggregates of alpha-synuclein protein in neurons, nerve fibers or glial cells. "In contrast, risk variants in cathepsin B and D genes were identified in synucleinopathies, which support the involvement of these proteases in the mechanism of disease." (PMID 35573838, 2022). "Moreover, low levels of CTSB have been found in PD CSF samples, indicating that reduced activities of CTSD and CTSB are strongly associated with PD and other synucleinopathies." (PMID 37312133, 2023). "Variants in CTSB and GBA interact to mediate genetic risk for PD and given the established importance of GCase in mediating risk of synucleinopathy this raises the question of whether the impaired α-syn clearance observed following catB impairment is partially mediated by secondary GCase impairment." (PMID 39587654, 2024). "Taken together, our data confirm that externally administered cysteine proteases CTSB and CTSL promote the clearance of SNCA species in vitro, ex vivo as well as in vivo, providing a new therapeutic approach for the treatment of synucleinopathies." (PMID 40883786, 2025).
astrocytoma (5 papers, 2009 to 2021). "We analyzed 350 astrocytomas for autophagy-associated markers LC3B, p62, BAG3, Beclin1 and the lysosomal markers LAMP2 and Cathepsin B (CTSB) to investigate whether also the lysosomal machinery is altered." (PMID 26956048, 2016).
brain injury (5 papers, 2022 to 2025). Acute and chronic (see also brain INJURIES, CHRONIC) injuries to the brain, including the cerebral hemispheres, CEREBELLUM, and brain STEM. "Increased levels of cathepsin B in the cytosol, plasma, and CSF have been associated with cognitive dysfunction in Alzheimer’s and traumatic brain injury." (PMID 35444632, 2022). "CTSB affects the nervous system by regulating neuronal synaptic plasticity, and the inhibitors of cathepsin B have the potential to be the therapeutic agents for traumatic brain injury." (PMID 39038939, 2024).
breast tumor (5 papers, 2014 to 2024). "Of the total of 340 breast tumors that were successfully analyzed for cathepsin B, 95 (28%) showed a high (TIS 6–12) and 245 (72%) a low (TIS 0–5) expression." (PMID 39331316, 2024). "In contrast, all breast tumors in this study express cathepsin B, L, and/or S to some extent and approximately 90% of tumors stained for all three cathepsins show high expression levels of at least one of these proteases, which could make this technique less prone to intertumoral heterogeneity." (PMID 39331316, 2024). "When the FRRG-MMAE nanoparticles are intravenously injected into the breast tumor-bearing mice, they efficiently accumulate within the tumor tissues by enhanced permeability and retention (EPR) effect and release free MMAE by cathepsin B overexpressed in tumor cells." (PMID 36297566, 2022). "Meanwhile, FRRG-MMAE nanoparticles significantly minimized the MMAE-related toxicity toward normal tissues owing to their innately low cathepsin B. As a result, efficient tumor delivery of MMAE by FRRG-MMAE nanoparticles greatly inhibited the breast tumor growth with minimal side effects." (PMID 36297566, 2022).
cerebral aneurysm (5 papers, 2015 to 2025). "Additionally, CTSB has been linked to cerebral aneurysm formation, with research highlighting its role in vascular remodeling and aneurysm development [1105]." (PMID 40407975, 2025). "A cerebral aneurysm was created surgically in mice, and it was demonstrated by immunohistochemistry methods that after three months of follow-up, the levels of cathepsin B, S, and K in the aneurysmal tissues increased and the cystatin C level decreased." (PMID 33224650, 2020). "Murine models show that treatment with E-64d, a non-selective cysteine protease inhibitor, provides neuroprotection after trauma, functioning primarily through inhibition of cathepsin B and administration of NC-2300, a selective cystine protease inhibitor, reduces the incidence of cerebral aneurysm." (PMID 34409065, 2021). "Moreover, in human cerebral aneurysm tissue, cathepsin B is highly expressed in the endothelial cell layer and the media in the aneurysmal walls in contrast to control artery tissue where it is barely expressed at all." (PMID 26388830, 2015). "Brain aneurysms and vascular ECM degradation occur as a result of TBI, and cathepsin B inhibition stopped aneurysm progression and vascular ECM degradation in brain aneurysm and ischemic animal models." (PMID 26388830, 2015).